MTOR (mechanistic target of rapamycin kinase)
Diseases named in the same sentence as MTOR in open-access papers (continued):
Sharing a sentence is not in itself a finding about the gene and the disease.
tumor (continued). "Studies have shown that in tumour cells, PI3K and mTOR are involved in the regulation of SG formation." (PMID 39080255, 2024). "It was found that FKC treatment suppressed tumor volume and weight and inhibited glycolysis and angiogenesis-related protein expression and phosphorylation of the EGFR/PI3K/Akt/mTOR pathway, whereas knockdown of HSP90B1 strengthened the effect of FKC." (PMID 38711062, 2024). "NOP56 and mTOR cooperate to maintain homeostasis in response to oxidative stress and significantly enhance cell death in KRAS mutant tumor cells." (PMID 39712244, 2024). "In mTOR-driven HCC models, tumor cells also enhance arginine uptake while reducing its conversion to polyamines, thus promoting oncogenic metabolism through the arginine-binding protein RNA binding motif protein 39 (RBM39)." (PMID 39610917, 2024). "Another mTOR inhibitor, torkinib (PP242), was also treated with rapamycin (ABI-009), resulting in reduced tumor formation ability and aldehyde dehydrogenase 1 (ALDH1) activity, inducing autophagy." (PMID 39349424, 2024). "For instance, Erianin can exert anti-tumor effects through the ERK pathway, ROS mediated JNK/c-Jun and AKT/mTOR pathways, PI3K/AKT/mTOR pathway, calcium/calmodulin dependent ferroptosis pathway." (PMID 39605083, 2024). "The activation of mTOR pathway is closely related to the proliferation of HCC, tumor metabolic reprogramming and tumor angiogenesis." (PMID 38461206, 2024). "In terms of tumor autophagy, the HMGB1/RAGE axis induces cellular autophagy through signaling pathways involving PI3K-AKT-MDR1, mTOR, NF-kB, MAPK, and p-ERK1/2." (PMID 38529373, 2024). "FOXO1 and mTOR, which are essential proteins in the PI3K/PTEN/AKT network, were shown to be engaged in tumor cell progression, migration, apoptosis, and radiation resistance during RT." (PMID 38965615, 2024). "Seven genes passing these filters were involved in various aspects of tumour biology, including cell survival and DNA repair (CASP9, NDRG1, and XPA), mTOR signalling (TSC1), and transcription and RNA processing (ETV6, ISY1, and SMAD2)." (PMID 39660592, 2024). "In tumor immunology, PI3K-Akt-mTOR pathway is important in modulating immune cell functions and shaping the TME, influencing the outcomes of antitumor immune responses." (PMID 39483536, 2024). "Aberrant activation of the IGF-IR/PI3K/Akt pathway seems to contribute to the activation of mTOR, which results in the growth and proliferation of MLS tumor cells." (PMID 39456230, 2024). "These 6 target genes were positively correlated with pathways related to tumor progression, such as the WNT/Beta-Catenin and PI3K/AKT/mTOR signaling pathways." (PMID 38840234, 2024). "Small molecule activators of AMPK, mTOR, or PGC-1α also show a synergistic suppression of tumor growth when combined with PD-1 blockade." (PMID 38891056, 2024). "Several reports have shown that EMT can be regulated by regulating PI3K/AKT/mTOR or WNT signaling pathways, thereby affecting tumor invasion and metastasis." (PMID 39324007, 2024). "Using the GEPIA2 web tool, AKT1, MAPK1, and mTOR expression levels were compared between PDAC and a normal population (for tumor tissues, n = 197, and for normal tissues, n = 171)." (PMID 38553450, 2024).
tumor (continued). "Recent research has established the close relationship among the mTOR pathway, glycolysis, and GLUT3 expression in tumor cells." (PMID 39668819, 2024). "They then analyzed the mTOR pathway activation (p-S6 and p-4EBP1) and administered EVE to assess its effect on tumor growth." (PMID 39736867, 2024). "We therefore explored the relevance of the PI3K/mTOR pathway for ICB treatment in uLMS and explored pharmacological inhibition of this pathway to sensitise these tumours to ICB." (PMID 38711203, 2024). "This molecule influences the activity of VEGFA, ERBB, mTOR, TGF-β, and the PTEN/PI3K/AKT pathway, thereby affecting the process of tumor angiogenesis." (PMID 39001478, 2024). "NAT1 overexpression inhibits the PI3K/AKT/mTOR signaling pathway, thereby suppressing the EMT (epithelial-mesenchymal transition) process and glycolytic ability of tumor cells." (PMID 38916406, 2024). "Collectively, these findings indicate that silencing of Gαi3 by aav-shGαi3-s1 injection effectively suppressed Akt-mTOR activation and YAP/TAZ activity in priPC-1 xenografts, and inhibiting tumor growth." (PMID 39349432, 2024). "Consistently, in our study, we proved that PL resulted in the reduction of the p-PI3K/p-AKT/p-mTOR/JAK2/p-STAT3 and the augment of the p-p38/p-ERK1/2/p-JNK in the H22 tumor-bearing mice." (PMID 38240856, 2024). "A further activator of the AKT/mTOR pathway in PMe is speculated to be the hepatocyte growth factor receptor (c‐Met), the dysregulation of which contributes to the regulation of cell growth, motility, and invasion, as well as confers tumours the ability to metastasize." (PMID 38459714, 2024). "Through its lipid phosphatase activity, PTEN control a variety of tumor cell progressions, such as proliferation, apoptosis, invasion and metastasis by regulating PI3K/Akt/mTOR, FAK, Raf/MEK/ERK signaling pathway." (PMID 38167440, 2024). "GC-HER2 overexpression induces PI3K/AKT/mTOR and MAPK activation, promoting tumor-cell survival, proliferation, adhesion, and migration." (PMID 38339127, 2024). "PTEN is a tumor suppressor involved in the regulation of several signalling pathways, including the PI3K/AKT, FoxO, AMPK, and mTOR pathways." (PMID 38811809, 2024). "Tumor cells with overactivated PI3K, Akt, mTOR, KRas, and c‐Myc positively regulate glutamate metabolism to produce α‐KG, which enters the TCA cycle and provides energy through GLUD or transaminase catalysis." (PMID 39584783, 2024). "Given its involvement in tumour development and progression, the phosphoinositide 3-kinase (PI3K)/AKT/mammalian target of rapamycin (mTOR) pathway has emerged as a promising therapeutic target in GBM." (PMID 38615034, 2024). "Currently, classic medications for advanced RCC targeted therapy involve the development of tumor inhibitors that target the VEGF/VEGFR signaling pathway and the PI3K/Akt/mTOR signaling pathway." (PMID 39669571, 2024). "One of the mechanisms for tumor cell-stimulated expression of PD-L1 is the activation of EGFR, PI3K/mTOR, or MAPK signaling pathways." (PMID 39113885, 2024). "In terms of tumor proliferation, the HMGB1/RAGE axis promotes tumor cell growth through several signaling pathways, including NF-kB, K-Ras, MAPK, AKT, mTOR, STAT3, MEK, and ERK1/2." (PMID 38529373, 2024). "Overall, this result suggested that PLCG2 promoted tumor cell proliferation, invasion, metastasis, and EMT and inhibited apoptosis through activation of the Akt-mTOR signaling pathway, thereby facilitating CRC progression." (PMID 39494327, 2024). "The activation of HSP results in the stabilization of several tumor‐promoting HSP clients such as AKT, mTOR and HSF1 itself, which substantially accelerates tumor development." (PMID 39049197, 2024).
tumor (continued). "The results suggested that downregulation of tumor suppressive miR-99b-5p mediates the upregulation of the mTOR/AR/SMARCD1 signaling axis, consequently promoting tumor aggressiveness and metabolic reprogramming in AA PCa and CRPC." (PMID 38256166, 2024). "By targeting both AKT and mTOR, PI3K inhibitors comprehensively block multiple signaling pathways that drive tumor growth and BC progression." (PMID 38172946, 2024). "In terms of tumor apoptosis, the HMGB1/RAGE axis mediates tumor cell death through signaling pathways involving NF-kB, AKT, mTOR, and ERK1/2." (PMID 38529373, 2024). "Dactolisib (BEZ235) is a dual inhibitor of PI3K and mTOR that can downregulate the AKT-mTOR-HIF1α signaling pathway, inhibiting tumor-induced angiogenesis and promoting cell death through apoptotic pathways." (PMID 39769140, 2024). "In the endothelial cells of mice infected with the KSHV v-GPCR, mTOR knockdown can interfere with the paracrine transformation of v-GPCR by increasing the accumulation of dephosphorylated 4EBP, thereby inhibiting the tumor growth." (PMID 38817860, 2024). "In the tumor microenvironment, CXCLs/CXCR-2 cascade can signal through RAS/ERK, PI3K/AKT/mTOR, PKC/p38/NF-κB, JAK/STAT3 and PLD to regulate DNA damage, senescence, angiogenesis, survival, proliferation, migration and further administration of chemokines." (PMID 38672477, 2024). "They found that the combination of mTOR, VEGFR2, c-Kit and c-RAF was the most significant predictor of response to sorafenib, resulting in a tumor response rate of 15.6%." (PMID 38993637, 2024). "For example, KLK10 modulates tumor growth and glucose metabolism in CRC through the PI3K/Akt/mTOR pathway." (PMID 38585643, 2024). "Heparanase promotes tumor progression via the PI3K/AKT/mTOR signaling pathway, which is specifically correlated with the phosphorylation of AKT and mTOR." (PMID 39247596, 2024). "Inhibition of mTOR and downregulation of GPX4 protein synergistically can be a potential therapeutic mechanism for anti-tumor." (PMID 38583115, 2024). "OPN promoted tumor sphere formation and angiogenesis in TNBC by activating the PI3K/AKT/mTOR pathway to regulate GPX4-mediated anti-lipid peroxidation levels." (PMID 38526702, 2024). "It acts as a tumor suppressor by directly interacting with PCDH8 and inhibiting the PI3K/AKT/mTOR signaling pathway." (PMID 39065771, 2024). "Our tests demonstrated receptor-mediated uptake of FA-pRNA-PI-103 nanoparticles, pH-responsive PI-103 drug release from lysosomes and inhibition of the PI3K/mTOR pathway in CRC cells and tumor spheroids." (PMID 40115434, 2024). "Lidocaine, which reduces tumor cell viability in a time- and dose-dependent manner, has been reported to inactivate the PI3K/AKT/mTOR signaling pathway and promote autophagy." (PMID 38482052, 2024). "By using the xenograft tumor mouse model, we found that PI3K/Akt/mTOR activation in tumor was obviously reduced by using EpoY." (PMID 39443476, 2024). "Oncogenic signalling pathways, such as PI3K/AKT/mTOR, JAK/STAT, Hippo, and NF-kB, intersect with the lipid metabolism to drive tumour progression." (PMID 38610991, 2024). "Further GSEA analysis indicated that high EMP1-expressing tumor cells were significantly enriched in aging (NES = 1.58, p = 0.001), focal adhesion (NES = 1.821, p < 0.001), and PI3K/AKT/mTOR pathways (NES = 1.522, p = 0.001)." (PMID 40612666, 2024). "Various studies suggest that ARL4C plays a crucial role in intensifying tumor proliferation, invasion, and drug resistance via immune-related pathways, which include Wnt/β-catenin, AKT/mTOR, and MEK/ERK." (PMID 38404591, 2024). "Research has indicated that the anti-tumor effects of metformin are mainly due to the activation of AMP-activated protein kinase (AMPK) and inhibition of mammalian targets of rapamycin (mTOR)." (PMID 38962452, 2024).
tumor (continued). "mTOR signaling pathway can normally activate GLUT1, a key glycolysis protein, which can enhance the Warburg effect of tumor cells through the transcription factors HIF1α and MYC." (PMID 39003253, 2024). "Second, a multitude of downstream substrates of Akt, including FoxO, mTOR, MDM2, and NF-κB, influence the survival, proliferation, and metabolism of tumor cells through their downstream effectors, ultimately determining cell fate." (PMID 39537605, 2024). "A recent study proposed that cathepsin K secreted by tumor cells binds to TLR4, leading to the M2 polarization of TAMs through an mTOR-dependent mechanism." (PMID 39148909, 2024). "GPER1 promotes tumor progression mainly by interacting with carcinogenic signaling pathways, such as the EGFR/ERK1/2 pathway, the PI3K/AKT/mTOR signaling pathway, and the MAPK/ERK signaling pathway." (PMID 38383297, 2024). "FAN has been reported to attenuate tumor migration and invasion by downregulating the c-Met/PI3K/AKT/mTOR and Wnt/β-catenin signaling pathways." (PMID 39000284, 2024). "Inflammation activates oncogenic signaling pathways including NF-κB, MET, STAT3, mTOR and MAPK, leading to tumor progression and an aggressive phenotype." (PMID 38561856, 2024). "Mechanistically, BDS-hEA prominently facilitated autophagic apoptosis in tumor tissues and decreased the levels of ki67, CD31, VEGF, MMP-9, p-AKT, and p-mTOR while simultaneously enhancing the p-AMPK expression." (PMID 39091624, 2024). "Studies have found that multiple miRNAs in the tumor microenvironment promote the expansion and immunosuppression of MDSCs by targeting inhibiting PTEN and activating the PI3K/AKT/mTOR or STAT3 signaling pathways." (PMID 39206155, 2024). "Apatinib, an oral highly potent tyrosine-kinase inhibitor targeting VEGFR2 was observed to show the synergistic effect on anti-tumor activities of cisplatin on MDA-MB-231 TNBC cells by downregulating the levels of VEGFR2, AKT, and mTOR." (PMID 38892472, 2024). "CHK2, CDKL1, PKA[alpha], Akt1/PKB[alpha], mTOR/FRAP, Akt2/PKB[beta], ATR, PKG1, RSK2 were the top 10 upstream kinases with higher activity in tumor than in normal kidney." (PMID 39724752, 2024). "Analysis of human MB tumor samples (N = 952) revealed a positive correlation between OTX2 and mTOR mRNA expression, emphasizing the clinical significance of OTX2’s role in the mTORC2 pathway." (PMID 38674001, 2024). "We further investigated the TCGA database obtained from UALCAN software, which indicates the upregulation of AKT, mTOR, ETV7, and TAZ in tumor patients." (PMID 38791386, 2024). "HER-2, two tumour suppressor genes; breast cancer gene 1 (BRCA1), and breast cancer gene 2 (BRCA 2), and cell angiogenesis gene mTOR (all primers were purchased from willowfort.co.uk) were tested in the present study." (PMID 39103402, 2024). "PC often involves the activation of the mTOR/PI3K/AKT pathway, which facilitates tumor growth, disease progression, and resistance to treatment." (PMID 39351434, 2024). "MiR-196b was found to accelerate GC tumor growth by promoting cell cycle and cell proliferation, possibly by activating the PI3K/Akt/mTOR pathway." (PMID 38230216, 2024). "With the deepening of immunometabolic studies, it has been shown that PI3K/Akt/mTOR and LKB1-AMPK, as core immunometabolic signaling pathways, can largely influence tumor progression in the continuous crosstalk between immune and metabolic signals." (PMID 38755125, 2024). "Simultaneously, we performed a parallel analysis of the levels of p-AMPK, p-mTOR, p-ULK1, and BMF in tumor tissues via Western blotting." (PMID 39598428, 2024). "OPN promotes tumor progression and angiogenesis in oral cancer through the activation of the PI3K/Akt/mTOR signaling cascade." (PMID 39062100, 2024).
tumor (continued). "Targeting the PI3K/Akt/mTOR pathways is a promising strategy in cancer, and possible in VHL treatment due to their central role in tumor biology, potential to overcome resistance, and ability to enhance the effectiveness of existing therapies." (PMID 39272694, 2024). "Inhibitors of vascular endothelial growth factor receptor (VEGFR, e.g., sunitinib and axitinib) and mTOR (e.g., everolimus) exhibit anti-tumor activity in ccRCCs, largely due to the activation of angiogenesis and the PI3K-AKT-mTOR signaling." (PMID 38301040, 2024). "Experimental studies have shown that chrysin can inhibit tumor progression by regulating the H19/let-7a/COPB2, P38-MAPK/Akt and Akt/mTOR pathways and affecting mitochondrial function and ER stress." (PMID 38742934, 2024). "Research highlights the crucial role of miRNAs in key cellular processes, showcasing their intricate interactions with the oncogenic PI3K/AKT/mTOR (PAM) signaling pathway and underscoring their significant role as tumor suppressors." (PMID 38504785, 2024). "T-cell apoptosis induced by intra-tumor ROS underscores the beneficial effect of glutathione (GSH) in priming T-cell responses and metabolic reprogramming through the activation of mTOR, NFAT, and MYC." (PMID 38891056, 2024). "SNORA38B plays a role in promoting tumor progression in NSCLC by directly binding to E2F transcription factor (E2F1) and regulating the GAB2/AKT/mTOR pathway thereby contributing to the development of an immunosuppressive tumor microenvironment." (PMID 38406265, 2024). "The combination of these agents has been shown to synergistically inhibit tumor cell proliferation and induce apoptosis, primarily through the suppression of the phosphoinositide 3-kinase (PI3K)/AKT/mTOR signaling axis." (PMID 39857585, 2024). "Fasting favors the accumulation and activation of gd T cells in breast tissue and strengthens the anti-tumor immune response of cytotoxic CD8 T cells by producing ketone bodies and inhibiting mTOR activity." (PMID 37568713, 2023). "It was suggested that prolonged TGF‐β treatment activates mTOR and epithelial‐mesenchymal transition (EMT), resulting in stemness maintenance and tumour expansion." (PMID 37156724, 2023). "HALLMARK enrichment analysis showed that pathways related to tumor growth and invasion, such as mTORC1 signaling, PI3K/Akt/mTOR signaling, G2M checkpoint and Myc signaling were significantly enriched in the high-CRIRS group." (PMID 37600770, 2023). "We found tumor-derived lactate enhanced PD-1 expression on Tbet+NK1.1− ILCs within the TME, which resulted in dampened the mammalian target of rapamycin (mTOR) signaling along with increased fatty acid uptake." (PMID 37098069, 2023). "Our research indicates that treating with ferulic acid significantly reduces the expression of mTOR and STAT3, leading to a decrease in the tumor." (PMID 37465088, 2023). "A mouse model of orthotopic tumor xenografts derived from KLC primary cells was established, and then the mice were treated with the FDA-approved mTOR inhibitor everolimus (E) alone or in combination with the MEK inhibitor trametinib (E + T)." (PMID 38124228, 2023). "AKT/mTOR/SREBP signaling by insulin and growth factors is the preliminary axis in anabolic metabolism, which assembles substances related to the tumor." (PMID 36768977, 2023). "Overexpression of lncRNA H19 inhibits mTOR phosphorylation and promotes ULK1 phosphorylation, thereby inhibiting the development of autosis and promoting tumor cell proliferation." (PMID 37313458, 2023). "Mechanistically, ZNF704 function as an oncogene by down-regulates SORBS3, which we demonstrated is a tumor suppressor in UM, and in turn activates PI3K/AKT/mTOR signaling pathway." (PMID 37038184, 2023).